FASN (fatty acid synthase)
Diseases named in the same sentence as FASN in open-access papers (continued):
Sharing a sentence is not in itself a finding about the gene and the disease.
tumor (continued). "FASN is an oncogenic protein that protects tumor cells against cisplatin-induced apoptosis." (PMID 39757995, 2025). "Moreover, the authors found that FASN overexpression functionally rescued the tumor-suppressive phenotypes induced by circHIPK3 knockdown in GBC cells." (PMID 40466438, 2025). "The overactivity of FASN not only facilitates tumor growth but also contributes to immune evasion by altering membrane composition and signaling pathways, ultimately creating a more favorable environment for tumor survival." (PMID 40376583, 2025). "The expression levels of FASN and ACC are not only associated with tumor aggressiveness and prognosis but may also serve as predictive biomarkers for the efficacy of immunotherapy." (PMID 40391753, 2025). "Additionally, tumor cells can regulate key molecules in fatty acid metabolisms, such as fatty acid synthase and lipoxygenase, to affect the activation and function of immune cells, thus creating an immunosuppressive microenvironment." (PMID 39950116, 2025). "Additionally, c-Myc also affects the lipid metabolism reprogramming of tumor cells by regulating genes related to fatty acid metabolism, including ATP citrate lyase, acetyl CoA carboxylase α, stearoyl CoA desaturase and fatty acid synthase (FASN)." (PMID 40718778, 2025). "This suggests that inhibiting FASN expression may enhance tumor cell sensitivity to chemotherapy drugs." (PMID 40936898, 2025). "Thus, the combination of FASN inhibitors and cisplatin can synergistically inhibit tumor growth and metastasis, and improve patient prognosis." (PMID 39757995, 2025). "For instance, the treatment of EC cells with inhibitors of ACACA, ELOVL1, or FASN would directly test the hypothesis that increased de novo lipogenesis promotes tumor growth." (PMID 40244177, 2025). "Reducing lipid synthesis with FASN inhibitors slows tumour progression and prolongs survival." (PMID 38553479, 2024). "FASN also connects to cellular metabolism and tumor immunomodulation." (PMID 38581001, 2024). "Thus, targeting FASN can enhance antitumor immunity, and has the potential to be a unique approach to tumor immunotherapy." (PMID 38272906, 2024). "The dysregulation of FASN has been linked to a more aggressive tumor phenotype in in-vitro studies, but so far it has not been selected as a prognostic marker in transcriptomic signatures using real-world patient cohorts." (PMID 39342345, 2024). "Here, we were interested in determining whether the key lipogenic enzyme FASN could impair immune-mediated cytolysis of tumor cells." (PMID 39349429, 2024). "Tumor tissues of 212 BC patients were subjected to tissue microarray and further assessed the associations of TC2N expression with pathological parameters and FASN expression." (PMID 38167440, 2024). "As described in previous studies, FASN protein was upregulated in tumor glands compared with adjacent benign epithelial cells and this difference was statistically significant across 115 normal-tumor pairs (P < 0.0001)." (PMID 38112617, 2024). "On the one hand, FASN participates in tumor immunity by regulating the infiltration of immune cells in the tumor immune microenvironment; on the other hand, FASN participates in tumor immunity by directly affecting the differentiation and function of immune cells." (PMID 38272906, 2024). "Notably, majority targets of TB-2 are implicated in tumor therapy, including TGM2, KIT, EGFR, AURKA, FASN, and CDK2, which have garnered extensive research attention." (PMID 39376614, 2024). "Interestingly, an increased expression of FASN and stearoyl-CoA desaturase 1 (SCD1) is associated with high levels of MUFA and monounsaturated PC in TC tissue compared to non-tumor tissue." (PMID 39000236, 2024).
tumor (continued). "Exposure to interferon-γ (IFNγ) during T-cell-mediated immune surveillance leads to an “immunometabolic editing”, whereby tumor cells coordinate the simultaneous activation of FASN and immune checkpoints such as programmed death ligand-1 (PD-L1) to maximize tumor proliferation and immune evasion." (PMID 39349429, 2024). "The results demonstrated that overexpression of FASN promoted tumor growth." (PMID 39345091, 2024). "In the SHH subtype of MB, the regulation of specific metabolic genes, including hexokinase 2 (Hk2) and fatty acid synthase (FASN), by Hedgehog (Shh) was found to shift the metabolic pattern toward aerobic glycolytic metabolism and lipid synthesis to maintain tumour growth." (PMID 38553479, 2024). "One study showed that the PI3k-α-specific inhibitor CYH33 facilitates the infiltration and activation of T cells by promoting FASN-mediated fatty acid metabolism while weakening the proliferation of M2-like macrophages and Treg cells; this boosts host immunity and inhibits tumor growth." (PMID 38272906, 2024). "Notably, PCa was the most common (ranked first) FASN-overexpressing tumor among all tumor types in TCGA database, suggesting the specific and important physiological functions of FASN in PCa." (PMID 39309439, 2024). "Fatty acid synthase (FASN), a fatty acid synthesis enzyme, has increasingly become a potential therapeutic target for many tumors, and elevated FASN expression significantly correlates with tumor promotion and radioresistance." (PMID 38291470, 2024). "Although FASN oncogenic activity seems to reside in its pro-lipogenic function, cumulating evidence suggests that FASN’s tumor-supporting role might also be metabolic-independent." (PMID 39064589, 2024). "Our group and others have established the tumor promoting role of FASN in CRC." (PMID 38732103, 2024). "It was found that knocked-out FASN obviously inhibited tumor growth and intrahepatic metastasis." (PMID 39075049, 2024). "As a key enzyme in fatty acid synthesis, FASN may serve as a new target for antitumor therapy and play an important role in tumor diagnosis and treatment." (PMID 38431720, 2024). "In addition to glycolysis, lipid metabolism is also dysregulated in HB, with increased fatty acid synthesis driven by fatty acid synthase (FASN) contributing to tumor growth." (PMID 39596558, 2024). "Then, combining their results with our results about TC2N inhibits FASN in all BC cell lines with different subtypes, we here from a side explains that the existence of TC2N is probably used for blocking neddylated PTEN/FASN axis-mediated tumor progression in all the four subtypes of BC." (PMID 38167440, 2024). "SREBP activity is upregulated in tumor Tregs and inhibits FASN-dependent FA synthesis." (PMID 38302980, 2024). "In addition, FASN can adjust the immune microenvironment and take part in epithelial-mesenchymal transition, thereby regulating tumor progression." (PMID 38218866, 2024). "Our findings suggested FASN as a novel tumor promotor in BC." (PMID 39071712, 2024). "Prior to this, we first discuss whether the TC2N/FASN axis-mediated tumor progression is BC subtype-dependent?" (PMID 38167440, 2024). "Tumor FASN expression has been shown to be part of an immune-related signature that informs an immunosuppressive TME characteristic of immune-excluded tumors that may benefit from certain types of immune checkpoint inhibitors (ICIs)." (PMID 39349429, 2024). "And further results prove the anti‐tumor status of CBR4 in the GEP‐NETs by decreasing the expression of FASN in an ubiquitin proteasome manner, which might provide a new inspiration for treatment." (PMID 39524139, 2024). "For instance, FASN has been correlated with tumor initiation." (PMID 38833109, 2024).
tumor (continued). "In line with the RNA sequencing data, P4BH, FASN, AKR1B1, and CBG5 proteins, which have a high prognostic risk, were upregulated in tumor tissues, and MYC proteins, which have a low prognostic risk, were downregulated in tumor tissues compared with normal controls." (PMID 39749345, 2024). "Similarly, FASN is highly expressed in ovarian cancer and can inhibit the capacity of tumor-infiltrating DCs (TIDCs), thereby reducing the ability of T cells to fight tumors." (PMID 38272906, 2024). "FASN is a novel tumor cell-intrinsic metabolic checkpoint that restricts T cell immunity and may be exploited to improve the efficacy of T cell-based immunotherapy." (PMID 39349429, 2024). "Our research describes FASN as a putative marker of immune evasion landscapes and suggests that this lipogenic enzyme may function as a constitutive mechanism that tumor cells use to resist and counteract cytolytic T-cell attack." (PMID 39349429, 2024). "Interestingly, the combination of two different FASN inhibitors with an anti-PD-L1 antibody enhanced the efficacy of immunotherapy and induced a dramatic inhibition of tumor growth in vivo." (PMID 39624081, 2024). "High 2-HG in IDH1 MT tumors increases the consumption of NADPH and limits the availability of NADPH for de novo lipogenesis, raising the possibility that such tumor cells could be selectively vulnerable to FASN inhibition in IDH1 MT tumors." (PMID 39149696, 2024). "FASN promoted tumor growth and resistance of DLBCL to ADM, both in vitro and in vivo." (PMID 39345091, 2024). "Moreover, in tumor growth and survival, FASN (fatty acid synthase) plays a crucial role, according to recent evidence." (PMID 38184562, 2024). "Reduced citrate metabolism through ACLY and FASN downregulation may correlate with altered lipid composition in vitamin C‐treated conditions, which helps the tumor to be more sensitive to gemcitabine." (PMID 38425123, 2024). "The deletion of FASN and inhibition of lipid synthesis could trigger apoptosis in intra-tumoral Treg cells, leading to a potent anti-tumor response and reduced tumor growth." (PMID 39275200, 2024). "We also examined the expression of the lipogenic gene FASN in tumor tissues." (PMID 38630355, 2024). "Inhibiting FASN not only reduces cell growth in various cancer models, including leukemia, but also lowers PD-L1 expression on tumor cells, offering a therapeutic avenue to reprogram T-cell metabolism and potentially shield them from tumor-induced immunosuppression." (PMID 38891056, 2024). "Tumor cells also upregulate de novo fatty acid synthesis to support membrane biosynthesis and energy storage by increasing the expression of key enzymes such as fatty acid synthase (FASN) and acetyl-CoA carboxylase (ACC)." (PMID 39610917, 2024). "We investigated whether CD155 is also related to fatty acid metabolism, and discovered, that changes in FASN regulated the expression of CD155 on the surface of tumor cells." (PMID 38291470, 2024). "Importantly, we here report TC2N to be a tumor suppressor that blocks fatty acid synthesis through preventing neddylated PTEN-mediated FASN stabilization." (PMID 38167440, 2024). "Fatty acid synthase (FASN) inhibition can partially restore the function of tumor-infiltrating DCs." (PMID 36677919, 2023). "However, FASN inhibitors have been tested in vivo at concentrations that are well tolerated in mice and that also led to inhibition of tumor growth, findings which were consistent with results from in vitro experiments." (PMID 37444561, 2023). "Correspondingly, FASN showed elevated expressions in tumor tissues (Fig. 4f1, g1)." (PMID 37164975, 2023). "FASN inhibitors inhibit the energy supply of tumor cells and disrupt their membrane composition." (PMID 37064872, 2023). "Furthermore, disease stage and tumor metastasis were also found to be related to FASN expression, as high FASN expression was consistent with worse disease stage and tumor metastasis." (PMID 37283794, 2023).
tumor (continued). "This hypothesis was substantiated by the finding that inhibition of FASN can induce cell cycle arrest and cell apoptosis and reduce tumor size." (PMID 37124526, 2023). "Overall, our collective findings offer valuable insights into the critical role of the ALKBH5/FABP5/FASN/mTOR axis in tumor progression and uncover a potential mechanism linking lipid metabolism to development of CRC, providing novel therapeutic targets for future interventions." (PMID 37416772, 2023). "Additionally, a proteomic analysis of tissue samples of a Wilms tumor confirmed that the expression of FASN was significantly increased in the tumor tissues as compared to adjacent tissues and this was associated with a poorer prognosis." (PMID 36834678, 2023). "Importantly, combination of FASN inhibitor and cetuximab can suppress the tumor growth of patient-derived xenografts that have CSN6/FASN overexpression." (PMID 37202390, 2023). "In addition to orlistat, we evaluated another FASN inhibitor C75 for its effect on tumor growth advantage driven by CSN6." (PMID 37202390, 2023). "Based on tumor grade, FASN expression decreased in advanced stages of PDAC, but increased in PCa." (PMID 36650542, 2023). "We collected paired adjacent normal (N) and tumor (T) tissue samples from 12 CRC patients, and the results showed that the expression of both CSN6 and FASN was elevated in tumor tissues compared to adjacent normal tissues and that their expression level was positively correlated in tumor tissues." (PMID 37202390, 2023). "In addition to FASN, the expression of other genes related to fatty acid metabolic process was also found to be changed in tumor cells." (PMID 37124526, 2023). "Furthermore, FASN was genetically knocked down using siRNA in tumor spheres, and this essentially inhibited the transcriptome of OPA1, resulting in a 50% reduction of OPA1 mRNA levels." (PMID 36809297, 2023). "In addition, mice bearing xenografts of esophageal squamous cell carcinoma cells (Colo680N) treated with the FASN inhibitor C93 showed a significant inhibition of tumor growth." (PMID 36934087, 2023). "Besides FASN, a variety of enzymes participating in the de novo production of fatty acids exhibit tumor-enhancing properties in CRC, rendering them appealing targets for therapy." (PMID 37689664, 2023). "Finally, we evaluated the expression of ACACA and FASN in tumour tissues obtained from xenograft experiments using human TNBC cells using immunohistochemistry." (PMID 37268670, 2023). "In support of these observations, the literature data shows that HER2-amplified cell lines and tumor samples both have elevated FASN and ACAT1 function (fatty acid synthesis), leading to poor prognosis and inhibitors to such targets enhance the efficacy of anti-HER2 therapies." (PMID 37414767, 2023). "Additionally, changes in ACC, FASN, and intracellular citrate levels indicated a decrease in fatty acid formation within both tumor cell lines when exposed to LX2-conditioned media." (PMID 37762298, 2023). "One of the reasons for this result is that the sample size of this study was relatively small, and it may also be possible that FASN plays an important role in early tumor transformation." (PMID 37056351, 2023). "In addition, we analyzed UM liver metastases from patients and observed marked FASN expression in the tumor tissue area." (PMID 37444561, 2023). "Hence, by targeting FASN, anti-tumor immunity can be enhanced by reducing lipid accumulation-induced dysfunction in dendritic cells." (PMID 38060103, 2023). "Furthermore, we show that the EGF pathway facilitates tumor-promoting metabolic programs by elevating the steady-state expression of CSN6/FASN in CRC cells." (PMID 37202390, 2023). "Tumor cells usually exhibit a high affinity for fatty acids and cholesterol to support their growth, and many lipogenic enzymes, such as fatty acid synthase (FASN), ATP‐citrate lyase (ACLY), and acetyl‐CoA carboxylase (ACC), are overexpressed in gastrointestinal cancers." (PMID 37860928, 2023).
tumor (continued). "Cer, as a fatty acid synthase inhibitor, could effectively inhibit phospholipid synthesis and lipid remodeling in tumor cells and reduce the migration and invasive ability of tumor cells." (PMID 37958697, 2023). "During the study, the results revealed a significant correlation between FASN expression level and tumor size, indicating that FASN may play an important role in tumor growth." (PMID 37124526, 2023). "Importantly, knockdown or inhibition of FASN dramatically suppressed tumor progression, both in vivo and in vitro." (PMID 37416772, 2023). "However, increased FASN expression was correlated with large tumor size (OR, 2.04; 95% CI, 1.04-4.00; P=0.038), higher human epidermal growth factor receptor 2 (HER2) positivity (OR, 1.53; 95% CI, 1.05-2.23; P=0.028)." (PMID 37124526, 2023). "As a key enzyme in fatty acid synthesis, FASN plays an important role in tumor progression." (PMID 37497413, 2023). "We further examined the roles of FABP5 and FASN in vivo with the aid of tumor xenograft models." (PMID 37416772, 2023). "FASN inhibitors also prevent tumor metastasis after the withdrawal of antiangiogenic therapy." (PMID 37064872, 2023). "A previous study demonstrated that FASN could prevent anti-tumor immunity by disrupting tumor-infiltrating dendritic cells." (PMID 37696831, 2023). "The results confirm that antagomir‐EBV‐miR‐BART18‐3p decreased EBV‐miR‐BART18‐3p expression and also demonstrate that antagomir‐EBV‐miR‐BART18‐3p decreased the levels of LDHA and FASN, as well as Ki67 (a recognized tumor malignant phenotype marker) in tumor tissues." (PMID 36307872, 2022). "FASN was differentially expressed between normal and tumor tissue, and was related to survival." (PMID 35392075, 2022). "Taken together, these results demonstrated the tumor therapeutic effect of FASN inhibition by mir-195-5p and future studies may take a new direction into the involvement of mir-195-5p and FASN in the tumor immune response." (PMID 36555243, 2022). "Moreover, both USP22 and FASN were significantly upregulated in CRC tumor tissues compared with the paired paracancerous non-tumor tissues." (PMID 36333288, 2022). "In brief, as revealed by the results and data of this study, FASN may be a novel target for preventing tumor metastasis, which provides a new reference for anticancer therapy." (PMID 35785165, 2022). "On the contrary, the high expression of FASN had a positive effect on the prognosis of anti-PD-L1 patients, which may be due to the specific effect of FASN on tumor cells and tumor-infiltrating immune T cells, which requires further study." (PMID 36555243, 2022). "Therefore, we performed IHC staining to visualize SREBP-1 and FASN expression following the TA3 treatment in subcutaneous BxPC-3 tumor tissue." (PMID 35631531, 2022). "Consistently, the higher expression level of indispensable genes for DNL, including ATP citrate lyase (ACLY), acetyl-CoA carboxylase alpha (ACACA), and fatty acid synthase (FASN) were observed in tumor tissue, further corroborating the pronounced DNL during hepatocarcinogenesis." (PMID 35406630, 2022). "The findings demonstrated that genes associated with FASN were predominantly enriched in pathways regulating essential functions of tumor cells, such as fatty acid metabolism, non-homologous recombination repair, and other processes." (PMID 36555243, 2022). "Fatty acid synthase (FASN) promotes tumor progression in multiple cancers." (PMID 36555243, 2022). "Targeting FASN upregulation of the tumour-promoting pathway can enhance anti-tumour immunity." (PMID 36439419, 2022). "In addition, IHC analysis and oil red O staining of tumor tissues indicated that USP13-dependent FASN expression increases lipogenesis." (PMID 35898882, 2022). "Second, the precise mechanism through which FASN is implicated in immune modulation and tumor immunotherapy responsiveness in malignancies has not yet been experimentally validated." (PMID 36555243, 2022).